NEAT1 (nuclear paraspeckle assembly transcript 1)
Diseases named in the same sentence as NEAT1 in open-access papers (continued):
Sharing a sentence is not in itself a finding about the gene and the disease.
glioblastoma (continued). "In addition, ALKBH5-stabilized NEAT1 can significantly suppress hypoxia-induced tumor-associated macrophage (TAM) recruitment and immunosuppression in glioblastoma." (PMID 36011001, 2022). "Furthermore, NEAT1 can target microRNA let-7 g-5p (miR let-7 g-5p) and negatively regulate its expression in glioblastoma." (PMID 34416900, 2021). "NEAT1 (nuclear enriched abundant transcript 1, or nuclear paraspeckle assemblytranscript 1) is an interesting example of oncogenic lncRNAs that has been wellstudied in glioblastomas." (PMID 34707896, 2021). "Similarly, expression of NEAT1 has been lower in the TMZ-sensitive glioblastoma tissues and cell lines compared with TMZ-resistant ones." (PMID 34178658, 2021). "In addition, let-7 g-5p is a downstream target of NEAT1 and can be negatively regulated by NEAT1 in glioblastoma stem cells." (PMID 34416900, 2021). "The NEAT1/miR-132/SOX2 axis regulates glioblastoma cells invasiveness, and, therefore, could be explored for treatment of this tumor type." (PMID 32283739, 2020). "STAT3 and NF-κB, two downstream effectors of EGFR signaling, could bind to and activate the NEAT1 promoter in glioblastoma." (PMID 30374364, 2018). "As previously reported, NEAT1 was upregulated in glioblastoma (GBM) tissues." (PMID 27556696, 2016). "For instance, NEAT1, a glioblastoma-associated lncRNA, was an oncogenic factor that was regulated by EGFR pathway, by activating WNT/β-Catenin pathway to promote GBM cells growth and invasion." (PMID 34772911, 2021). "However, it has been reported that lncRNA NEAT1 can affect glioblastoma cell growth and invasion by inducing trimethylation of H3K27 in the promoter regions of Axis inhibition protein 2, inhibitor of β-catenin and T cell factor, and glycogen synthase kinase 3B or by regulating EZH2 levels." (PMID 32157157, 2020). "When NEAT1 recruits EZH2 to the promoter region of the genome locus, the repression of these genes contributes to the progression of cancers such as glioblastoma." (PMID 36011001, 2022). "It has been reported that lncRNA NEAT1 binds to the histone methyltransferase EZH2 and subsequently inhibits the expression of the downstream target genes in glioblastoma." (PMID 33901015, 2021). "Furthermore, the interaction between NEAT1 and EZH2 triggers trimethylation of H3K27, which activates the WNT/β-catenin pathway, thereby increasing the malignancy of glioblastoma." (PMID 39043634, 2024). "In glioblastoma, PTRF can increase the stability of NEAT1 to promote cancer metastasis." (PMID 36011001, 2022). "The interaction between NEAT1, miR-132, and SOX2 has an important role in glioblastoma." (PMID 32283739, 2020). "In glioblastoma multiforme (GBM), ALKBH5 regulated the m6A modification of lncRNA NEAT1, leading to increased expression of interleukin-8 (IL-8), which promoted macrophage recruitment." (PMID 39220683, 2024).
non-small cell lung carcinoma (44 papers, 2015 to 2025). A group of at least three distinct histological types of lung cancer, including non-small cell squamous cell carcinoma, adenocarcinoma, and large cell carcinoma. "NEAT1 is an oncogenic lncRNA, and its elevated expression level has been associated with the progression of non-small-cell lung cancer." (PMID 29303984, 2018). "For example, NEAT1 might be associated with tumorigenesis and progression in non-small cell lung cancers." (PMID 28938549, 2017). "NEAT1 might also be associated with tumorigenesis and progression in non-small cell lung cancers (NSCLC)." (PMID 26911892, 2016). "Long noncoding RNA NEAT1 plays a significant role in ferroptosis sensitivity and drug resistance in non-small-cell lung cancer." (PMID 40078365, 2025). "For instance, lncRNA NEAT1 regulates ferroptosis sensitivity in non-small-cell lung cancer by interacting with ACSL4 and GPX4." (PMID 39280701, 2024). "Existing evidence has shown that NEAT1 acts as an oncogene in most types of cancer (non-small cell lung cancer, pancreatic cancer, osteosarcoma, renal cell carcinoma and so on), while in acute promyelocytic leukemia, it functions as a tumor suppressor." (PMID 36864364, 2023). "The silencing of lncRNA NEAT1 can enhance erastin-mediated ferroptosis in non-small-cell lung cancer cells by increasing intracellular lipid peroxidation, indicating the involvement of NEAT1 in the regulation of ferroptosis sensitivity." (PMID 37046995, 2023). "There have studies reported that NEAT1 was overexpressed during cancer development, including papillary thyroid cancer and non-small cell lung cancer." (PMID 31462890, 2019). "In sphere-forming cells generated from certain non-small cell lung cancer cell lines, downregulation of NEAT1 resulted in a significant decrease in the expression of CSC markers (CD133, CD44, ABCG2, Sox2, Nanog, and Oct-4)." (PMID 30374364, 2018). "A rencent study showed that the long non-coding RNA, NEAT1, promotes non-small cell lung cancer progression via regulation of the miR-377/E2F3 pathway." (PMID 29050301, 2017). "Other identified lncRNAs included LUCAT1, which is important in non-small cell lung cancer, NEAT1, and HELLPAR." (PMID 28957348, 2017). "In non-small cell lung cancer, through the sponging of miR-153-3p, NEAT1 downregulation could inhibit non-small cell lung cancer cell proliferation, migration, and invasion while encouraging cell death." (PMID 40165339, 2025). "Additionally, the methyltransferase METTL3 induced m6A modification of lncRNA NEAT1 to stabilize NEAT1 expression, thereby accelerating tumorigenesis in non-small cell lung cancer." (PMID 38351022, 2024). "Ovarian cancer and non-small-cell lung cancer (NSCLC) cells were made more susceptible to DDP when supplemented with EGCG by increasing ROS generation and CTR1 expression through activating the ERK1/2/NEAT1 pathway." (PMID 38572428, 2024). "In this section, we summarize the roles of the NEAT1/miRNA/target axis in respiratory system tumors, including nasopharyngeal carcinoma, sinonasal squamous cell carcinoma, laryngeal squamous cell cancer, and non-small cell lung cancer." (PMID 34512157, 2021). "Furthermore, NEAT1 has also been found to serve as a competing endogenous RNA against let-7a, which can diminish its expression in the context of non-small cell lung cancer." (PMID 34416900, 2021). "NEAT1 overexpression promotes non-small cell lung cancer proliferation and invasion in vitro." (PMID 32983133, 2020). "Furthermore, the knockdown of NEAT1 could reverse the paclitaxel resistance in non-small cell lung cancer (NSCLC) by inducing apoptosis by increasing cleaved PARP and cleaved caspase-3 expression." (PMID 38356722, 2024). "Shikonin induced apoptosis of paclitaxel-resistant non-small cell lung cancer (NSCLC) cell lines and xenograft tumors through suppressing NEAT1 and Akt signaling." (PMID 32839531, 2020).
non-small cell lung carcinoma (continued). "Serum lncRNAs, SPRY4-IT1, ANRIL, NEAT1, XIST and HIF1A-AS1 were identified as the potential predictor for the tumorigenesis of non-small-cell lung cancer." (PMID 26674525, 2015). "Recent study found that the NEAT1 could target binding with ACSL4 and downregulate the expression of ACSL4, resulting in decreased sensitivity of non-small cell lung cancer (NSCLC) cells to ferroptosis." (PMID 35910359, 2022). "A study demonstrated the role of NEAT-1 with a combination of different miRNAs in cancer diseases stating that the expression of NEAT-1 was significantly high in cancer cases and positively correlates with malignant features in general including late stages of non-small-cell lung cancer (NSCLC)." (PMID 39184920, 2024).
pancreatic cancer (39 papers, 2016 to 2025). "Neat1−/− mice were shown to be resistant to DMBA/TPA-induced skin carcinogenesis, whereas in other experiments, Neat1−/− mice were more susceptible to Ras oncogene-driven pancreatic cancer initiation." (PMID 36366537, 2022). "Conversely, NEAT1 deficiency was shown to impair paraspeckle formation and promote pancreatic cancer initiation." (PMID 33138914, 2020). "Loss of Neat1 in a KrasG12D-driven mouse model of pancreatic cancer has been shown to promote the development of premalignant pancreatic intraepithelial neoplasia (PanIN) and cystic lesions." (PMID 32727085, 2020). "Additionally, NEAT1 overexpression suppresses the transformation pancreatic cancer cells, and this effect was associated with an increase in the number of paraspeckles." (PMID 33138914, 2020). "Furthermore, in pancreatic cancer, the loss of NEAT1 increases the rate of acinar-to ductile metaplasia (ADM), a process of dedifferentiation, which is an early stage of pancreatic cancer formation." (PMID 33143162, 2020). "Previous studies have also shown that NEAT1 expression is significantly upregulated during the progression of pancreatic cancer." (PMID 39412616, 2025). "According to the GEPIA2 and TCGA databases, NEAT1 is highly expressed in pancreatic cancer and is positively correlated with ADAM8." (PMID 39412616, 2025). "In pancreatic cancer (PC) cells, NEAT1 can enhance the resistance of PC cells to gemcitabine by promoting EMT process." (PMID 38970092, 2024). "NEAT1 was reported to be highly expressed in pancreatic cancer tissues, and the knockdown of NEAT1 suppressed the growth of pancreatic cancer cells." (PMID 36612299, 2023). "In pancreatic cancer NEAT1 acts as tumor suppressor by regulating the expression of pancreatic differentiation genes." (PMID 37365156, 2023). "For example, RELA binds to the promoter region of nuclear paraspeckle assembly transcript 1 to regulate its expression, which therefore modulates pancreatic cancer cell proliferation and migration." (PMID 35812178, 2022). "NEAT1 was also found to regulate the growth, invasion, and migration of pancreatic cancer cells through microRNA-335-5p/c-met." (PMID 34222227, 2021). "NEAT1 was indicated to be overexpressed in pancreatic cancer and increased cell proliferation and metastases in pancreatic cancer cells." (PMID 33281873, 2020). "In pancreatic cancer, NEAT1 facilitated its oncogenicity by directly binding to miR-506-3p, the miRNA that has been reported as a tumor suppressor in diverse cancers." (PMID 30894512, 2019). "NEAT1 is required to suppress transformation in oncogene-expressing fibroblasts and in pancreatic cancer cells and to inhibit pancreatic cancer initiation in vivo." (PMID 31835405, 2019). "ADAM8 regulates intracellular STAT3 levels via miR-181a-5p and NEAT1 in pancreatic cancer." (PMID 39412616, 2025). "In pancreatic cancers, NEAT-1 can promote growth by modulating levels of miR-335-5p." (PMID 28122578, 2017). "Thus, this study clarified a possible mechanism by which EV-encapsulated NEAT1 from adipose-derived mesenchymal stem cells (ADSCs) might mediate gemcitabine resistance in pancreatic cancer (PCa)." (PMID 36762032, 2023). "Interestingly, the role of NEAT1 in pancreatic cancer seems to be controversial." (PMID 32727085, 2020). "Hence, based on their abundance, significant downregulation and their prognostic relevance, LINC00261 and NEAT1 might be interesting candidates for functional follow-up studies to dissect their cellular and molecular functions in pancreatic cancer." (PMID 32727085, 2020). "Among them, pancreatic cancer cells in the cluster 8 with TIMP1+/FN1+ showed the strongest resistance, while the cluster 1 with CLDN18-/CEACAM5- and the cluster 7 with HSPA6+/NEAT1+ showed milder resistance." (PMID 38343537, 2024). "As illustrated by the examples of NEAT1 and the TGF-β pathway, the roles of lncRNAs and the processes involving them may change dynamically as pancreatic cancer progresses." (PMID 40427100, 2025).
pancreatic cancer (continued). "Indeed, in developed pancreatic cancer and fully transformed PDAC cell lines, human NEAT1 has mostly been assigned oncogenic roles." (PMID 40427100, 2025). "NEAT1 competitively binds to miR-146b-5p to attenuate the inhibitory effect of miR-146b-5p on TRAF6, thereby increasing the expression of TRAF6 and promoting the proliferation, migration and invasion of pancreatic cancer cells." (PMID 38970092, 2024). "For instance, NEAT1 can sponge miR-302a-3p, which is a tumor-suppressive molecule that suppresses the translation of RELA mRNA, thereby upregulating RELA and increasing the migration and proliferation capacity of pancreatic cancer cells." (PMID 36011001, 2022). "Study indicates that long non-coding RNA NEAT1 facilitates pancreatic cancer progression through negative modulation of miR-506-3p62." (PMID 29238093, 2017). "In addition, according to our results, NEAT1 was more up-regulated in pancreatic cancer tissue than that in paired non-cancerous tissue, which demonstrated that NEAT1 might act as a cancer promoter and participate in the process of tumorigenesis of pancreatic cancer." (PMID 28118609, 2017).
cervical carcinoma (38 papers, 2017 to 2025). A carcinoma arising from either the exocervical squamous epithelium or the endocervical glandular epithelium. "Given the crucial role of NEAT1 in cancer, identifying the function and underlying mechanism of NEAT1 in the metastasis of cervical cancer and investigating its therapeutic potential are highly important." (PMID 38733179, 2024). "In this study, we examined the role of NEAT1 in the progression of cervical cancer and the specific mechanism underlying its function." (PMID 38733179, 2024). "Suppressing NEAT1 expression hampers cervical cancer glycolytic activity, which has been widely associated with high PD-L1 expression, as well as with the inhibition of apoptosis, lactate production, and immunosuppressive processes, whereas its upregulation produces the opposite effect." (PMID 41195272, 2025). "The depletion of NEAT1 by siRNA caused the upregulation of miR-361 in cervical cancer cells." (PMID 32151082, 2020). "We then assessed the association between NEAT1 expression and overall survival of patients with cervical cancer using the online databases SurvExpress, where cervical cancer patients from the TCGA dataset (n = 191) were divided into low- and high-risk groups for poor prognosis." (PMID 32151082, 2020). "Therefore, the effects of miR-361 and NEAT1 expression on the secretion of HSP90 by cervical cancer cells should be explored using the enzyme-linked immunosorbent assay." (PMID 32151082, 2020). "Overall, we believe that NEAT1 reprograms the metabolism of cervical cancer cells, which positively regulates aerobic glycolysis and specifically inhibits mitochondrial oxidative phosphorylation." (PMID 38733179, 2024). "CCK‐8, colony formation, flow cytometry, western blotting, and Transwell assays were used to evaluate the impact of NEAT1 on the malignant behavior of cervical cancer cells." (PMID 38733179, 2024). "A series of rescue assays were performed to determine the essential role of WNT/β‐catenin signaling pathway in aerobic glycolysis and the progression‐promoting function of NEAT1 in cervical cancer." (PMID 38733179, 2024). "Overall, these results revealed that NEAT1 was highly expressed in human cervical cancer tissue and positively correlated with PDK1 and β‐catenin." (PMID 38733179, 2024). "In cervical cancer, the lncRNA NEAT1 has been identified as a contributor to tumor progression by activating the WNT/β-Catenin/PDK1 signaling axis." (PMID 39519092, 2024). "This study investigated the role and possible molecular mechanism of lncRNA nuclear paraspeckle assembly transcript 1 (NEAT1) in cervical cancer." (PMID 38733179, 2024). "The present study investigated a novel mechanism through which NEAT1 contributed to cervical cancer metastasis and malignant progression." (PMID 38733179, 2024). "The RT‐qPCR assay was used to detect the expression of NEAT1 in cervical cancer tissues and cell lines." (PMID 38733179, 2024). "Our study illustrated that NEAT1 modulates aerobic glycolysis in cervical cancer by upregulating PDK1 and promoted the migration, invasion and EMT of cervical cancer cells through aerobic glycolysis." (PMID 38733179, 2024). "Overall, we presumed that the promotion of cervical cancer progression by NEAT1 depends on the WNT/β‐catenin/PDK1 signaling axis." (PMID 38733179, 2024). "First, we compared NEAT1 expression in a human cervical squamous epithelial cell line (End1) and in human cervical cancer cell lines (SiHa, HeLa, C33a, Caski) using RT–qPCR." (PMID 38733179, 2024). "We observed that the enhanced lactate production and glucose consumption induced by NEAT1 overexpression were reversed after cervical cancer cells were treated with 2‐DG." (PMID 38733179, 2024). "In summary, this evidence suggested that NEAT1 promoted aerobic glycolysis and cervical cancer progression through WNT/β‐catenin signaling pathway." (PMID 38733179, 2024).